CCAT2 (colon cancer associated transcript 2)
Synonyms: NCCP1; LINC00873
Gene: Long non-coding RNA gene on chromosome 8 (127,400,399 to 127,402,150, forward strand). Ensembl gene ENSG00000280997.
Diseases named in the same sentence as CCAT2 in open-access papers:
CCAT2 is named in the same sentence as 61 diseases in open-access papers, as found by Europe PMC text mining. Sharing a sentence is not in itself a finding about the gene and the disease. The quoted sentences say what the papers report.
colorectal cancer (47 papers, 2014 to 2025). A primary or metastatic malignant neoplasm that affects the colon or rectum. "CCAT1 and CCAT2 are located in 8q24.21 and are frequently amplified in colorectal cancers, and their high expression of CCAT1 and CCAT2 is associated with poor prognosis." (PMID 38473243, 2024). "The lncRNA colon-cancer-associated transcript 2 (CCAT2) was first identified in colorectal cancer, and its upregulated expression in various types of cancer has been reported to promote tumor progression." (PMID 38540273, 2024). "Colon-cancer associated transcript 1 and 2 (CCAT1 and CCAT2) are two lncRNAs first described in primary colorectal cancer." (PMID 37347737, 2023). "Long non-coding RNAs (lncRNAs) CCAT1 and CCAT2 have previously been found to be associated with impaired patient outcomes in primary colorectal cancer." (PMID 37347737, 2023). "Wang and collaborators demonstrated that the lncRNA colon cancer-associated transcript 2 (CCAT2) was significantly overexpressed in colorectal cancer (CRC) tissues of CRC patients when compared to healthy controls." (PMID 36866275, 2023). "Surprisingly, the roles of CCAT1 and CCAT2 have previously been associated with unfavourable patient outcomes in various tumor diseases including primary colorectal cancer." (PMID 37347737, 2023). "CCAT2 (Colon cancer-associated transcript 2) is located on chromosome 8q24 with a 1752 bp lncRNA, which was initially identified in colorectal cancer." (PMID 35397764, 2022). "Analogously to PVT1, altered expression and genetic variations in two lncRNAs upstream of MYC, colon cancer‐associated transcripts 1 and 2 (CCAT1 and CCAT2), have also been correlated with increased susceptibility to colorectal cancer." (PMID 34668345, 2022). "Here, we investigated the clinicopathological and prognostic potential of the long noncoding RNA Colon Cancer-Associated Transcript 2 (CCAT2) in human colorectal cancer (CRC)." (PMID 34868956, 2021). "CCAT1 and CCAT2 were discovered as colorectal cancer associated transcripts but have also been shown to be involved in prostate tumorigenesis, among others." (PMID 32218194, 2020). "Colon cancer-associated transcript 2 (CCAT2), a 1752 bp lncRNA, located at 8q24.21, was originally detected as being highly expressed in colorectal cancer, promoting tumor process metastasis during carcinogenesis." (PMID 33371204, 2020). "The CCAT2 gene region contains a colorectal cancer associated SNP (rs6983267), and the risk allele was shown to promote CCAT2 overexpression." (PMID 33329688, 2020). "Several SNVs are implicated in the expression of cancer-associated lncRNAs—including CCAT2 in colorectal cancers and PCAT-1 in prostate cancer." (PMID 30934003, 2019). "CCAT1‐L transcript variant of the CCAT1 gene and CCAT2 are specifically expressed in colorectal cancer." (PMID 30451365, 2019). "Intriguingly, colon cancer-associated transcript 2 (CCAT2) expression was found upregulated in Colorectal Cancer (CRC) Exo." (PMID 31281356, 2019). "Colon cancer-associated transcript 2 (CCAT2)—An lncRNA that was identified for the first time in colorectal cancer—is increasingly detected in human cancers, and its overexpression is associated with poor clinical outcome." (PMID 30208633, 2018). "Later it was found that rs6983267 lies within a long non-coding RNA, CCAT2, and that colorectal cancer cell lines express significantly higher levels of CCAT2 transcripts containing the risk G allele." (PMID 29956121, 2018). "Specific instances of this type of effect have been observed in colorectal cancer risk loci where for example the risk SNP rs6983267 within 8q24 disrupts a chromatin regulatory network involving interactions between three genes CCAT2, CCAT1 and MYC." (PMID 28062664, 2017). "Other important lncRNAs, such as HOTAIR and CCAT2 have been showed that they have played critical roles in the development of colorectal cancers and are associated with poor prognosis in CRC." (PMID 29340086, 2017).
colorectal cancer (continued). "Colon cancer-associated transcript 2 (CCAT2), a novel noncoding RNA mapping to the 8q24 gene desert region, was firstly identified as oncogenic lncRNA in microsatellite-stable colorectal cancer." (PMID 27833083, 2016). "Subsequent studies have suggested that a specific SNP variation within this region may lead to increased CCAT2 expression and greater predisposition to colorectal cancer." (PMID 34668345, 2022). "CCAT2 has been used as a diagnostic and prognostic biomarker in the treatment of colorectal cancer." (PMID 34868956, 2021). "SNPs associated with cancer risk may involve cancer-driver lncRNAs, as exemplified by CCAT2 (colon cancer associated transcript 2), a lncRNA that encompasses the rs6983267 SNP and is overexpressed in microsatellite-stable colorectal cancer." (PMID 32503290, 2020). "Recent research reported that colorectal cancer cell lines overexpressing lncRNA CCAT2 showed a higher level of glucose uptake, lactic acid secretion, and oxygen consumption." (PMID 38243936, 2024). "At this point, we provide novel insight into lncRNA CCAT2/miR-145 axis regulated by Tec in the glycolysis of colorectal cancer." (PMID 38243936, 2024). "Our findings identified a novel mechanism of Tec for inhibiting colorectal cancer progression and suggested the significant implication of lncRNA CCAT2/ miR-145 axis for the treatment of CRC." (PMID 38243936, 2024). "Altogether, these results showed that Tec inhibited the proliferation and glycolysis via downregulating the expression of lncRNA CCAT2 in colorectal cancer cells." (PMID 38243936, 2024). "To further ascertain the influence of lncRNA CCAT2 on proliferation in colorectal cancer cells, we monitored cell viability by CCK-8 assay." (PMID 38243936, 2024). "Collectively, these results indicated that Tec inhibits the proliferation and glycolysis in colorectal cancer cells via regulating the lncRNA CCAT2/miR-145 axis." (PMID 38243936, 2024). "The novelty of the present study is to authenticate the effect of Tec on the proliferation and glycolysis of colorectal cancer via regulating the lncRNA CCAT2/ miR-145 axis in vitro and in vivo." (PMID 38243936, 2024). "Some examples of long non-coding RNA variants in this catalog include rs6983267 in CCAT2 regulating cancer metabolism through allele-specific binding of CPSF7 and rs2147578 in LAMC2-1 modulating microRNA binding to it in colorectal cancer." (PMID 35365203, 2022). "In order to assess CCAT2 expression, we first examined the levels of CCAT2 in 44 paired colorectal cancer (CRC) and adjacent normal tissues via qPCR." (PMID 34868956, 2021). "CCAT1 and CCAT2 are located in the 8q24.21 region, which is frequently amplified in colorectal cancer." (PMID 34321511, 2021). "LncRNA colon cancer-associated transcript 2 (CCAT2) is a 1,752 nucleotide sequence located in the chromosome 8q24 and expressed in microsatellite-stable colorectal cancers." (PMID 32154165, 2020). "For example, CCAT1‐L and CCAT2 form attractive targets to specifically inhibit MYC transcription in colorectal cancer." (PMID 30451365, 2019). "Microsatellite instability is a sign of DNA mismatch repair deficiency that can be inherited, which is involved in regulation of lncRNA gene function, e.g. CCAT2 in colorectal cancer." (PMID 30286721, 2018). "CCAT2 was found to positively regulate c-MYC transcription levels and thereby to affect the growth, metastasis and energy metabolism of colorectal cancer cells in an allele-specific manner." (PMID 29956121, 2018). "lncRNA CCAT2 is over-expressed in colorectal cancer and promotes tumor growth, metastasis and reduces sensitivity to chemotherapy that is associated with colon CSC and regulated by cooperation of miR-145 and miR-21." (PMID 28964256, 2017). "CCAT2, a novel noncoding RNA mapping to 8q24 chromosomal region, was originally detected as markedly high level in colorectal cancer." (PMID 27833083, 2016).
colorectal cancer (continued). "A recent study has shown that this SNP affects the expression of CCAT2, thereby impacting tumor growth and metastasis in colorectal cancer." (PMID 26430965, 2015). "CCAT1 and CCAT2 have also been reported to be closely related to colorectal cancer." (PMID 35992788, 2022). "It has been reported that the expression of CCAT2 significantly increases tumor-node-metastasis (TNM) and is associated with TNM, and may be a potential diagnostic biomarker for colorectal cancer." (PMID 34499007, 2021). "The overexpression of CCAT2 promoted colorectal cancer cell invasion, migration and wound-healing." (PMID 34868956, 2021). "To study whether CCAT2 is involved in colorectal cancer metastasis, we evaluated the effects of CCAT2 on the migration and invasion of colorectal cancer cells." (PMID 34868956, 2021). "For instance, lincRNA CCAT2 (Colon Cancer-Associated Transcript 2, also termed LINC00873), a transcript spanning SNV rs6983267, is associated with an increased risk for prostate, breast, colon, and colorectal cancers." (PMID 32523949, 2020). "For example, lncRNA CCAT2 was expressed at high levels in patients with colorectal cancer." (PMID 30925672, 2019). "Overexpression of Colon Cancer Associated Transcript 2 (CCAT2), which is localized in 8q24.21, can induce chromosomal instability by interacting with and stabilizing the BOP1 ribosomal biogenesis factor, leading to increased MYC expression in colorectal cancer." (PMID 40783798, 2025). "The lncRNAs CCAT1 and CCAT2, located in the 8q24.21 locus, were highly overexpressed in colorectal cancer and were significantly associated with recurrence-free survival (RFS) and overall survival (OS), which serve as important prognostic biomarkers in colorectal cancer." (PMID 31417644, 2019). "Several studies reported that certain lncRNAs contribute to the progression of colorectal cancer, such as HOTAIR, MALAT-1, and CCAT1/CCAT2." (PMID 38473243, 2024). "By analyzing the expression of 17 lncRNAs and 31 circRNAs in biopsies and serum exosomes from colorectal cancer (CRC) patients through qRT-PCR, we detected CCAT1, CCAT2, HOTAIR, and UCA1 upregulation and CDR1AS, MALAT1, and TUG1 downregulation in biopsies." (PMID 30195762, 2018). "In our studies, we investigated the impact of Tec on colorectal cancer cells HCT116 and explored whether Tec could exert inhibition of proliferation and glycolysis via the lncRNA CCAT2/miR-145 axis in vitro and in vivo." (PMID 38243936, 2024).
breast cancer (40 papers, 2013 to 2026). A primary or metastatic malignant neoplasm involving the breast. "Upregulation of CCAT2 (colon cancer-associated transcript 2) lncRNA was observed in breast cancer tissues and cell lines, besides being associated with poor prognosis." (PMID 34359587, 2021). "The expression of the lncRNA CCAT2 (Colon Cancer Associated Transcript 2) is increased in breast tumors and breast cancer cells relative to normal breast tissue/cells." (PMID 30545127, 2018). "To further discover the role of CCAT2 in breast cancer, we subsequently assessed the associations between its transcript levels and several clinicopathological characteristics." (PMID 28480695, 2017). "Taken together, these findings indicate that an elevated CCAT2 expression is associated with the progression and development of breast cancer." (PMID 27608009, 2016). "The group around George A. Calins lab was able to demonstrate that an elevated CCAT2 expression is associated with the development of metastases and poor prognosis within various cancers, including breast cancer." (PMID 27608009, 2016). "Subsequently, they found CCAT2 in many additional cancer types, such as cancer of the gastric, cancer of the cervical, and cancer of the breast." (PMID 41459628, 2026). "In mechanism, we found a greater distribution of CCAT2 in the cytoplasm of luminal breast cancer cells than in TNBC cells." (PMID 36672487, 2023). "Our previous work found a greater distribution of endogenous CCAT2 in the cytoplasm in the luminal subtype of breast cancer cells than that in TNBC cells." (PMID 36672487, 2023). "Compared to normal human mammary gland epithelial cell MCF-10A cell, CCAT2 showed downregulation in two luminal breast cancer cell lines MCF-7 and T47D." (PMID 36672487, 2023). "In order to further determine the function of CCAT2 in the nucleus of the luminal subtype of breast cancer, a pMX retrovirus vector was applied to introduce exogenous CCAT2 into the nucleus of MCF-7 cells, followed by functional analyses." (PMID 36672487, 2023). "In order to determine the expression pattern of CCAT2 in the luminal subtype of breast cancer, we analyzed CCAT2 in cancer cell lines and patients’ tumor samples." (PMID 36672487, 2023). "Colon cancer-associated transcript 2 (CCAT2) enhances proliferation and decreases apoptosis in tamoxifen-resistant cells, and the reduction in CCAT2 provides a new approach for breast cancer patients." (PMID 37104009, 2023). "Cytoplasmic CCAT2 in the luminal subtype of breast cancer cell MCF-7 or T47D significantly suppressed cell proliferation and cancer cell stemness in vitro." (PMID 36672487, 2023). "Herein, we found the cytoplasmic distribution of CCAT2 after pcDNA3.1-mediated transfection in luminal breast cancer cells, while pMX-mediated stable overexpression of CCAT2 maintained CCAT2 in the nucleus." (PMID 36672487, 2023). "Herein, we found a dual function of long non-coding RNA CCAT2 in the luminal subtype of breast cancer, depending on its subcellular distribution." (PMID 36672487, 2023). "Transient overexpression of CCAT2 in the luminal subtype of breast cancer cell MCF-7 or T47D significantly suppressed cell proliferation in vitro and inhibited tumor growth in vivo." (PMID 36672487, 2023). "OCT4-PG1 showed induction by nuclear CCAT2 in luminal breast cancer cells, consistent with our previous report that CCAT2 induced cancer cell stemness in TNBC partly through promoting OCT4-PG1 expression." (PMID 36672487, 2023). "CCAT2 showed an overall downregulation in the tumor tissues from the luminal breast cancer patients." (PMID 36672487, 2023).
breast cancer (continued). "Since miR-221/222 can interact with the mRNA of p27, thereby decreasing the expression level of p27 in breast cancer cells, we further analyzed the expression of p27 before and after transfection of CCAT2 in MCF-7 cells." (PMID 36672487, 2023). "In order to determine the function of CCAT2 in luminal breast cancer cells, we transiently overexpressed CCAT2 using pcDNA3.1 plasmid in MCF-7 or T47D cells, followed by cell proliferation analysis and colony formation assay." (PMID 36672487, 2023). "Herein, we found a dual function of long non-coding RNA (LncRNA) CCAT2 in the luminal subtype of breast cancer, depending on its subcellular distribution." (PMID 36672487, 2023). "Meanwhile, a correlation analysis between the patients’ survival and CCAT2 expression indicated better disease-free survival in those CCAT2high patients with luminal breast cancer." (PMID 36672487, 2023). "For instance, when CCAT2 lncRNA is expressed in breast cancer stem cells during targeted knockdown, it increases the levels of Nanog, OCT4, and KLF4, as well as the ALDH + CSC population which can serve as a marker for the presence cancer stem cells." (PMID 35864503, 2022). "Downregulation of lncRNA CCAT2 can inhibit the proliferation and invasion of breast cancer cells by regulating the TGF-β pathway and promoting the apoptosis of breast cancer cells." (PMID 34422811, 2021). "Previous independent reports have shown the overexpression of CCAT2 in breast cancer tissues, as well as overexpression of MYC in certain types of breast cancer." (PMID 28480695, 2017). "They showed CCAT2 overexpression in two out of three sets of patients and the correlation between transcript levels and clinical factors only for a subgroup of breast cancer patients." (PMID 28480695, 2017). "In the present investigation, we evaluated the expression of CCAT2 in breast cancer tissues in comparison with ANCTs and showed a significant CCAT2 overexpression in tumor samples in a subset of patients." (PMID 28480695, 2017). "Recently, lncRNAs such as lncRNA-ATB, GAS5, HOTAIR, CCAT2, H19, BCAR4, UCA1, LncRNA-ROR and LncRNA-ARA have been implicated in resistance to chemotherapy in breast cancer patients." (PMID 29299178, 2017). "Previous researchers showed that CCAT2 expression was highly expressed in various malignancies, such as breast cancer, gastric cancer, cervical cancer, esophageal cancer, ovarian cancer, and lung cancer." (PMID 29088900, 2017). "Increasing evidence shows that CCAT2 was shown to be consistently upregulated in esophageal squamous cell carcinoma, gastric cancer and breast cancer." (PMID 27833083, 2016). "Up-regulation of colon cancer associated transcript 2 (CCAT2) and EPB41L4A-AS2 is associated with the prognosis of breast cancer." (PMID 27589728, 2016). "CCAT2 was found to have increased expression in 2 out of 3 examined primary breast cancer patient sets, although a correlation between the rs6983267 genotype and CCAT expression was not identified." (PMID 25101115, 2014). "CCAT2 showed an overall downregulation in the tumor tissues from luminal breast cancer patients." (PMID 36672487, 2023). "Different from the triple negative subtype, herein, we showed the downregulation of CCAT2 in luminal breast cancer and found a positive correlation between the expression levels of CCAT2 and overall survival rate in the luminal subtype of breast cancer patients." (PMID 36672487, 2023). "Our study revealed a dual function of CCAT2 in the luminal subtype of breast cancer depending on its subcellular distribution, which will help improve our understanding of molecular mechanisms for breast cancer regulation by CCAT2." (PMID 36672487, 2023). "Consistently, a decrease in CCAT2 was observed in both luminal A and luminal B breast tumor samples, compared to matched adjacent normal mammary tissues, which was further confirmed in 609 luminal breast cancer tumors from the TCGA database." (PMID 36672487, 2023).